DKK3 (dickkopf Wnt signaling pathway inhibitor 3)
Diseases named in the same sentence as DKK3 in open-access papers (continued):
Sharing a sentence is not in itself a finding about the gene and the disease.
tumor (continued). "In our previous study, we found that extracellular MIR92a packed within microvesicles secreted by CRC cells is delivered into endothelial cells and contributes to the proliferation and motility of these cells through down-regulation of Dikkopf-3 (Dkk-3), a presumed tumor suppressor gene." (PMID 32759718, 2020). "To conclude, we identify a key role of DKK3 in tumour stroma." (PMID 30631061, 2019). "Silencing of DKK3 partly alleviated the inhibition of tumor growth induced by miR-92a inhibitor." (PMID 30926679, 2019). "Our data thus demonstrated the DKK3 gene is a potential tumor suppressor gene in GBC and aberrant promoter methylation could be involved in its downregulation, which may play a role in the tumorigenesis and aggressiveness of GBC." (PMID 31737564, 2019). "Thus, DKK3 acts as a crucial integrator of key molecular players modulating the emergence of tumour-promoting phenotypes in CAFs." (PMID 30631061, 2019). "In summary, we identified DKK3 as a novel functional tumor suppressor gene in GBC." (PMID 31737564, 2019). "Furthermore, dickkopf-related protein 3 (DKK3) has been identified as a tumour suppressor, and DKK3 is typically used as a cancer biomarker and therapeutic target." (PMID 31423109, 2019). "Our results suggested that E2F3 might play a tumour-promoting role in the metastasis and progression of GC by regulating the miR-125a/DKK3 axis." (PMID 31423109, 2019). "Our results suggest that HSF1-dependent DKK3 upregulation could be a response of stromal fibroblasts to stresses found in the tumour microenvironment." (PMID 30631061, 2019). "Furthermore, HSF1 activity strongly correlated with DKK3 gene expression in the stromal compartment of human tumours." (PMID 30631061, 2019). "The initial evidence suggesting that DKK3 may play a role in the regulation of the tumour microenvironment came from analyses of stromal gene expression in normal and cancerous tissues." (PMID 30631061, 2019). "Considering the previous reports describing the tumor suppressive roles of DKK3, its inhibitory effect on malignant TGF-β signaling, and its potential in recent clinical trials, we have focused on reactivating endogenous DKK3 expression using a CRISPR-based approach." (PMID 29843383, 2018). "Expression of DKK-3 in tumor tissues is mostly located in microvascular ECs." (PMID 29695980, 2018). "DKK3 may contribute to the suppression of tumours by virtue of its ability to antagonize Wnt signalling." (PMID 29673070, 2018). "One of the tumor suppressive mechanisms described for DKK3 is its inhibition of cell proliferation." (PMID 29843383, 2018). "In addition, Dkk-3 is upregulated in the tumor endothelium, suggesting it plays a role in angiogenesis." (PMID 29858602, 2018). "The expression of the REIC/Dkk-3 gene is down-regulated in many tumor cell lines and could contribute to the immunomodulatory properties of the tissue microenvironment." (PMID 28978116, 2017). "The interesting finding was the positivity of Dkk-3 in the endothelial cells of tumor vessels." (PMID 28978116, 2017). "Reduced DKK3 expression is observed in a variety of solid tumors, and re-expression studies in multiple cancer cell types mostly resulted in cell cycle arrest and/or apoptosis, strongly suggesting a global tumor suppressor role for this WNT regulator." (PMID 28249601, 2017). "Due to its abnormal expression pattern, whether DKK3 acts as an oncogenic gene in HB patients remains unclear; further study is required to elucidate the function of DKK3, and its potential as a tumor therapy, in HB." (PMID 27788486, 2016). "Furthermore low DKK3 expression is significantly related to high tumor grade (P < 0.05), indicating a possible involvement of DKK3 in epithelial differentiation." (PMID 27467270, 2016). "Therefore, the in vivo anti-tumor effect of REIC/Dkk-3 protein largely depends on the induction of enhanced systemic anti-cancer immunity." (PMID 27625116, 2016).
tumor (continued). "The LV-miR-25 group displayed reduced DKK3 and Ki67 expression in the tumor tissues." (PMID 27801786, 2016). "Although DKK3 expression is down-regulated in most cancers, a recent study demonstrated that DKK3 is overexpressed in some HB patients, which is inconsistent with its typical tumor suppressor role." (PMID 27788486, 2016). "Moreover, several reports have demonstrated that Dkk-3 plays important roles in tumor suppression and declined level of Dkk-3 is reported in diverse types of cancer." (PMID 27329316, 2016). "Regardless, decreases in DKK3 expression in various cancers suggest that it may act as a tumor suppressor and serve as a therapeutic target." (PMID 27788486, 2016). "Significant involvements of Dkk-3 in tumor angiogenesis have also been reported." (PMID 27827955, 2016). "Since DKK3 has been reported to be produced by MSCs, we investigated whether DKK3 contributes to the immune suppression of anti-tumor responses by MSCs." (PMID 26734010, 2015). "We identified three tumour suppressor genes associated with Wnt signalling, namely, AXIN2, DKK3 and SFRP1, that could potentially be suppressed by miR-582-3p." (PMID 26468775, 2015). "Since then numerous reports proposed that DKK3 can act as a tumor suppressor." (PMID 26734010, 2015). "Thus, DKK3−/− MSCs were normally persistent and maintained their phenotypes within the tumor transplants." (PMID 26734010, 2015). "Thus, DKK3 expression by MSCs contributed to modulating the tumor microenvironment by limiting CD8+ T cell infiltration and promoting M2-type macrophage appearance." (PMID 26734010, 2015). "Therefore, we have chosen two models of tumor transplants whose progression is supported by MSCs to investigate the role of DKK3." (PMID 26734010, 2015). "It is suggesting that DKK3 may reverse the stem cell‐like phenotype of tumour cells in hypoxic conditions." (PMID 26395974, 2015). "In addition to these in vitro results, we found that the tumour size of DKK3 transfectants in nude mice was significantly decreased compared to control cells." (PMID 26395974, 2015). "Furthermore, we observed that RMA-mOVA tumor-infiltrating CD8+ T cells were significantly increased in tumors containing DKK3−/− MSCs in comparison to tumors containing WT MSCs (p = 0.0314), as we had already shown for the HCmel12 tumors." (PMID 26734010, 2015). "Based on these findings, we investigated whether DKK3 is involved in MSCs-mediated immune modulation of anti-tumor responses." (PMID 26734010, 2015). "Interestingly, TRAIL and DKK3, apart from inducing tumor-cell apoptosis, have also been shown to inhibit proliferation in several tumor and non-tumor cell types." (PMID 26378036, 2015). "To exclude the possibility that the observed decrease in tumor growth in the presence of DKK3−/− MSCs was due to poorer survival or loss of MSC characteristics in vivo, we compared the viability and MSC phenotypes of WT and DKK3−/− MSCs." (PMID 26734010, 2015). "DKK3 is also known as REIC (Reduced Expression in Immortalized Cells), as it was found to be down-regulated in many immortalized cell lines and a number of established human cancer lines, functioning as a natural tumor suppressor in human tissues." (PMID 26105053, 2015). "Therefore, the release of DKK3 by the MSCs, when activated with radiation, is a useful approach for the generation of anti-tumor immune responses in malignant cells." (PMID 26378036, 2015). "It had been reported that DKK3 produced by human MSCs could decrease cell cycle progression of tumor cells in vitro." (PMID 26734010, 2015). "Dkk3 is downregulated and considered to function as a tumor suppressor in a number of tumor types." (PMID 25029272, 2014). "Previously, significant downregulation of the REIC/Dkk-3 expression has been reported in a broad range of human malignant tissues and REIC/Dkk-3 is hypothesized to function as a tumor suppressor gene." (PMID 24527065, 2014).
tumor (continued). "Hypermethylation of the human Dkk3 promoter may be the mechanism for the downregulation in various tumour types, as is repression of Dkk3 by the MYCN regulated miRNA-92." (PMID 25029272, 2014). "Ad-REIC infection and REIC/Dkk-3 protein are also known to up-regulate the anti-tumor immunosystem." (PMID 24498395, 2014). "Expecting that transfection of REIC/Dkk-3 would provide therapeutic effects as a tumor suppressor gene, we previously developed an adenoviral vector expressing the human REIC/Dkk-3 gene (Ad-REIC) and demonstrated that the agent induced apoptosis in various cancer cell lines." (PMID 24398705, 2014). "Moreover, Dkk-3 and ANGPT2 were inversely regulated in human umbilical vein endothelial cells after knockdown of Axl 36, suggesting a role of Dkk-3 in tumor angiogenesis." (PMID 23765731, 2013). "Furthermore, Dkk-3 expression resulted in decreased cell motility as well as reduced tumor growth and pulmonary metastasis in an orthotopic xenograft model of OS." (PMID 23476112, 2013). "Furthermore, ITIH5 and DKK3 methylation achieved 40% sensitivity with a high specificity in healthy and benign disease controls." (PMID 23320751, 2013). "As Wnt/β-catenin signalling plays an important role in tumour metastasis, we thus investigated whether DKK3 counteracts this pathway for its tumour suppressive function." (PMID 23890219, 2013). "Ad-REIC/DKK3 has been used with success in preclinical studies demonstrating robust anti-tumor effects including induction of cancer cell specific apoptosis and inhibition of metastatic disease, and is currently in clinical trials for use in prostate cancer (see footnote 3; NCT01197209)." (PMID 23226679, 2012). "Overexpression of DKK3 has been shown to mediate potent anti-tumor effects including reduced cell proliferation, anchorage-independent growth, and invasion and metastasis, and induced cancer cell specific apoptosis both in vitro and in murine tumor models." (PMID 23226679, 2012). "Several lines of evidence exist to suggest that DKK3 acts as a tumor suppressor." (PMID 23226679, 2012). "However, it is conceivable that the elevated Dkk-3 levels in PCa SP are derived from the tumor neovasculature, where high levels of Dkk-3 are produced." (PMID 22071168, 2011). "Interestingly, injection of an adenovirus vector carrying DKK3 showed a dramatic anti-tumor effect in a xenograft human PCa model, inhibiting tumor growth and lymph node metastasis and prolonging mice survival." (PMID 20976069, 2010). "Interestingly, tumor suppressor genes such as DKK3 and gamma FBPα, the avian homolog of HIC-1 (hypermethylated in cancer 1), were repressed markedly by v-Src in CEF." (PMID 20152043, 2010). "Likewise, DFS at 10 years for patients harboring DKK3 methylation in the tumor was 58%, compared with 78% for patients with unmethylated DKK3 (p = 0.037)." (PMID 19570204, 2009). "Immortalisation, that is escape from cellular senescence, is an early event in malignant transformation, so DKK3 could act as a tumour suppressor gene by mediating the effects of senescence stimuli." (PMID 18826564, 2008). "Since DKK3 is thought to negatively regulate oncogenic Wnt signalling, DKK3 may be a potential tumour suppressor gene in normal breast tissue." (PMID 18826564, 2008). "As a consequence, loss of DKK3 may promote hyperactivation of the PCP pathway, thereby potentially enhancing tumour aggressiveness." (PMID 18826564, 2008). "This suggests that DKK3 may have an important tumour-suppressive function that either prevents tumour initiation or attenuates cancer progression." (PMID 18826564, 2008). "The human Dickkopfs-3 (Dkk-3) gene, located on chromosome 11p15.1 is a recently found mortalisation-related gene expression of which is largely attenuated in many immortalised and tumour-derived cell lines." (PMID 15226763, 2004).
tumor (continued). "Dkk-3 is a newly characterised mortalisation-related gene and an antagonist of the Wnt oncogenic signalling pathway whose expression is decreased in a variety of cancer cell lines, suggesting that the Dkk-3 gene, located at chromosome 11p15.1, functions as a tumour suppressor gene." (PMID 15226763, 2004). "Thus, DKK3 loss accelerates the earliest step of tumor initiation, whereas DKK3 induction can delay, but not abolish, KRAS‐mediated ADM, underscoring KRAS dominance." (PMID 41147409, 2026). "In BC, DKK3 orchestrates a concomitant activation of β-catenin and Yes-associated Protein 1 (YAP)/TAZ, where β-catenin is dispensable for CAFs-mediated ECM remodeling, cancer cell growth, and invasion, but DKK3-driven YAP/TAZ activation is required to induce tumor-promoting phenotypes." (PMID 39335478, 2024). "Interestingly, DKK-3 also exerts a tumor-suppressive function independently of Wnt signaling." (PMID 38201279, 2023). "While several reports highlighted a tumor suppressor role of DKK3 and its downregulation in various tumors including PCa, there is no full understanding of the molecular mechanisms through which DKK3 might produce this anti-tumorigenic effect." (PMID 36845147, 2023). "Therefore, unlike DKK 1, 2, and 4, there is still some debate about whether DKK3 is an oncogene or a tumor suppressor gene." (PMID 37149563, 2023). "However, other cells within the local tumor microenvironment and certain disseminated niches may also be important contributors of DKK3." (PMID 37847565, 2023). "Therefore, targeting DKK3 alongside other immunotherapeutic strategies may help break alternative suppressive barriers to eliminate dormant, residual tumor cells and more aggressive cells alike." (PMID 37847565, 2023). "In addition to the function of REIC/Dkk-3 as a tumor suppressor, previous studies showed that REIC/Dkk-3 may also exhibit angiogenic activity during embryogenesis and tumorigenesis." (PMID 36006934, 2022). "DKK3 may function as a tumor suppressor gene, and SPP1 functions as a cytokine resulting in increased interferon-gamma and interleukin-12 expression, and has been associated with enhanced tumor cell invasion and dissemination in EAC." (PMID 34638363, 2021). "Moreover, DKK-3 seems to be an effective inhibitor of tumor-cell growth molecules." (PMID 32354122, 2020). "Our results show that DKK3 may be a tumour suppressor in adult B‐ALL." (PMID 29673070, 2018). "Dkk-3 might also display angiogenic activity during embriogenesis and tumor development." (PMID 28352232, 2017). "Thus, the role of DKK3 in Wnt signaling might differ among tumor cell types, and investigating the precise Wnt pathways affected by DKK3 remains important." (PMID 28969056, 2017). "However, we would like to conclude that DKK3 is contributing to the immune-suppressive capacity of MSCs because DKK3 could reduce tumor infiltration by CD8+ T cells, which had been shown to contribute to the rejection of RMA-mOVA tumors." (PMID 26734010, 2015). "Therefore, the RMA-mOVA tumor cells, which do not express DKK3, were injected into DKK3-deficient mice." (PMID 26734010, 2015). "Thus the exact role and possible application of DKK3 may be dependent on the type of tumor and the cellular context." (PMID 26734010, 2015). "Thus, DKK3 could alter the composition of the tumor stroma, thereby supporting the MSCs-mediated suppression of immune responses against these tumor transplants." (PMID 26734010, 2015). "This suggested that DKK3 might be essential for MSCs to promote tumor growth." (PMID 26734010, 2015). "However, for some tumors the downregulation of Dkk3 is correlated with tumor progression." (PMID 25029272, 2014).
tumor (continued). "Thus, our findings demonstrate that DKK3 could function as a tumour suppressor through inducing apoptosis and regulating Wnt signalling during breast tumorigenesis." (PMID 23890219, 2013). "DKK3 is a tumour suppressor which could inhibit proliferation of many cancer cells." (PMID 19232135, 2009). "Indeed, it would be very interesting to pose the question that in view of the fact that DKK3 is considered to be a tumour suppressor gene whether it can also regulate MT1-MMP, suggesting a feed back loop." (PMID 18665176, 2008). "Furthermore, by transfection experiments, it has been determined that Dkk-3 possesses an antiproliferative activity against tumour cells, suggesting that Dkk-3 may function as a tumour suppressor." (PMID 15226763, 2004). "Interestingly, significantly higher levels of Fos – the previously identified downstream target of MAPK signaling – were found in DDKC cells, suggesting its potential role as a crucial driver of DKK3‐loss effects throughout tumor progression even in the absence of upstream MAPK signaling." (PMID 41147409, 2026). "Collectively, our data show that DKK3 acts cell‐autonomously to preserve acinar integrity in a KRAS wild‐type context and exerts a tumor‐suppressive role during KRASG12D‐driven PDAC progression." (PMID 41147409, 2026). "We also identified a previously unrecognized role of DKK3 in maintaining acinar integrity through the MEK‐Fos signaling axis, which contributes to delaying tumor progression." (PMID 41147409, 2026). "While DKK3 derived from CAFs in wild‐type pancreas enhances the oncogenic properties of cancer cells, its impact was notably more pronounced in DDKC tumor cells, which already displayed an aggressive mesenchymal phenotype." (PMID 41147409, 2026). "Furthermore, we could not determine any association of DKK-3 expression with the degree of differentiation, although the central mass of the tumours corresponded to a grade 2 carcinoma, as expected." (PMID 41007216, 2025). "Optically controlled Opt/Cas-Ad increased the expression level of Dkk-3 mRNA under blue light illumination and induced Dkk-3-mediated apoptosis in a PC3 cell xenograft tumor model." (PMID 40697381, 2025). "DKK3 belongs to the Dickkopf WNT signaling inhibitor family, which is known as a tumor-suppressor gene because of its inhibitory function of the oncogenic WNT signaling pathway." (PMID 40917921, 2025). "Dickkopf-3 (DKK3), part of the tumor endothelial marker family, is frequently silenced in CRC due to promoter hypermethylation." (PMID 40806747, 2025). "DKK3 protein inhibits oncogenic WNT signaling and functions as a tumor suppressor by competing with Wnt ligands binding to its receptor, Frizzled and LRP5/6, or blocking nuclear translocation of beta-catenin." (PMID 40917921, 2025). "Significant change of expression, reaching 10- to 58-fold change between uterine lesion compared to non-tumor counterpart, was observed in CAPN6, CD24, HMGA1, PLAG1, SNORA48, and SNORD10 (upregulation) and DKK3 and STK26 (downregulation)." (PMID 37466765, 2024). "In BC, POSTN-positive stromal cells were recently demonstrated to guide lymphovascular invasion by cancer cells, and DKK3 was demonstrated to orchestrate activation of YAP/TAZ, which is required to induce tumor-promoting phenotypes." (PMID 39335478, 2024). "The reduced expression of DKK3 can stimulate TGF-β signaling 28, which can help naïve T cells differentiate to Tregs 20, thereby preventing NK and CD8+ T cells from exerting anti-tumor effects." (PMID 39668827, 2024). "DKK-3, as implied by its other name, REIC (reduced expression in immortalized cells), is frequently downregulated in various tumor types, cancer cell lines and immortalized cells, as expected for a tumor suppressor." (PMID 38201279, 2023). "In the primary tumor, APLP2, BNIP3L, CD59 and DKK3 were highly expressed in 29.7% (n = 38), 64.9% (n = 83), 92.2% (n = 118) and 80.5% (n = 103), respectively." (PMID 35796776, 2023).